CSF2RB (colony stimulating factor 2 receptor subunit beta)
Description:
Cell surface receptor that plays a role in immune response and controls the production and differentiation of hematopoietic progenitor cells into lineage-restricted cells. Acts by forming an heterodimeric receptor through interaction with different partners such as IL3RA, IL5RA or CSF2RA. In turn, participates in various signaling pathways including interleukin-3, interleukin-5 and granulocyte-macrophage colony-stimulating factor/CSF2 pathways. In unstimulated conditions, interacts constitutively with JAK1 and ligand binding leads to JAK1 stimulation and subsequent activation of the JAK-STAT pathway.
Synonyms: CD131; IL3RB; IL5RB; betaGMR; CDw131; SMDP5
Tractability: Small molecule: it has a high-quality binding pocket. Antibody: a drug acting on it is in phase 2 or 3 trials; its Gene Ontology location is reachable by antibodies, with high confidence; UniProt predicts a signal peptide or a membrane-spanning region. PROTAC: ubiquitination databases record sites on it. Other modalities: a drug acting on it is in phase 2 or 3 trials.
Gene: Protein-coding gene on chromosome 22 (36,913,628 to 36,940,443, forward strand). Ensembl gene ENSG00000100368.
Subcellular location: Membrane
Subcellular location (Human Protein Atlas): Golgi apparatus
Pathways (Reactome):
Disease: Defective CSF2RA causes SMDP4; Defective CSF2RB causes SMDP5
Immune System: Interleukin receptor SHC signaling; Interleukin-3, Interleukin-5 and GM-CSF signaling
Metabolism of proteins: Surfactant metabolism
Signal Transduction: RAF/MAP kinase cascade
Gene Ontology:
Molecular function: coreceptor activity; protein binding; cytokine receptor activity; interleukin-3 receptor activity; interleukin-5 receptor activity; signaling receptor activity
Biological process: cell surface receptor signaling pathway via JAK-STAT; granulocyte-macrophage colony-stimulating factor signaling pathway; interleukin-3-mediated signaling pathway; interleukin-5-mediated signaling pathway; positive regulation of leukocyte proliferation; immunoglobulin mediated immune response; positive regulation of cell population proliferation; respiratory gaseous exchange by respiratory system; signal transduction; cellular response to interleukin-3; cytokine-mediated signaling pathway; response to lipopolysaccharide
Cellular component: granulocyte macrophage colony-stimulating factor receptor complex; external side of plasma membrane; interleukin-3 receptor complex; interleukin-5 receptor complex; plasma membrane; membrane
Genetic constraint (gnomAD): Loss-of-function variants: 26 observed, 70.57 expected, observed/expected ratio (o/e) 0.37, 90% interval 0.27 to 0.51. The upper end of that interval is the gene's LOEUF score, 0.51, which puts it in group 2 of 6, group 1 being the genes least tolerant of losing a copy. Missense variants: 1,113 observed, 1,197.1 expected, observed/expected ratio (o/e) 0.93, 90% interval 0.88 to 0.98. Synonymous variants: 507 observed, 494.12 expected, observed/expected ratio (o/e) 1.03, 90% interval 0.95 to 1.1.
Gene-disease validity (ClinGen):
ClinGen rates the evidence that CSF2RB causes each of these diseases.
surfactant metabolism dysfunction, pulmonary, 5 (autosomal recessive): Definitive.
Homologues: Orthologues: chimpanzee CSF2RB (98% identical), macaque CSF2RB (90% identical), dog CSF2RB (66% identical), pig CSF2RB (65% identical), rabbit CSF2RB (64% identical), mouse Csf2rb (56% identical), rat Csf2rb (56% identical), guinea pig CSF2RB (56% identical), mouse Csf2rb2 (56% identical), tropical clawed frog csf2rb (21% identical). Paralogues in human: EPOR (12% identical), IL4R (11% identical), MPL (11% identical), IL21R (9% identical), IL2RB (9% identical), IL9R (7% identical), IL7R (6% identical).
Diseases named in the same sentence as CSF2RB in open-access papers:
CSF2RB is named in the same sentence as 98 diseases in open-access papers, as found by Europe PMC text mining. Sharing a sentence is not in itself a finding about the gene and the disease. The quoted sentences say what the papers report.
pulmonary alveolar proteinosis (11 papers, 2014 to 2024). A rare lung disorder characterized by the filling of the pulmonary alveoli with proteinaceous material which stains positive with periodic acid-Schiff stain. "CSF2RB is associated with pulmonary alveolar proteinosis (PAP), which involves the accumulation of surfactant and macrophage dysfunction in alveoli (reviewed in 462)." (PMID 38577257, 2023). "Loss-of-function mutations in CSF2RB have been described in Crohn’s Disease and pulmonary alveolar proteinosis, resulting in defective GM-CSF-mediated STAT5 phosphorylation." (PMID 36532080, 2022). "According to the current understanding, Csf2- and Csf2rb-deficient mice develop pulmonary alveolar proteinosis (PAP) due to a defect in terminal maturation of AM involving impaired lipid catabolism." (PMID 24699679, 2014). "Pre-clinical studies investigated gene correction in hereditary pulmonary alveolar proteinosis with CSF2RA mutations and in surfactant protein B deficiency, while stem cells have been used to correct pulmonary alveolar proteinosis in CSF2RB deficient mice models." (PMID 33316882, 2020). "Induced pluripotent stem cells have been employed in a mouse model of pulmonary alveolar proteinosis (PAP) precipitated by CSF2RB deficiency." (PMID 39201839, 2024). "Similarly, mutations in the CSF2RA and CSF2RB genes in humans result in defective alveolar macrophage development and hereditary pulmonary alveolar proteinosis, which is associated with long-term respiratory insufficiency and high susceptibility to microbial infection." (PMID 35393945, 2022). "The mutation in CSF2RB can also cause hereditary pulmonary alveolar proteinosis (PAP)." (PMID 33553270, 2020).
leukemia (10 papers, 2019 to 2026). A malignant (clonal) hematologic disorder, involving hematopoietic stem cells and characterized by the presence of primitive or atypical myeloid or lymphoid cells in the bone marrow and the blood. "To date, no report(s) have been shown for the presence of potentially transforming and oncogenic CSF2RB mutation(s) clinically in cancer patients until the first reported case of a leukemia patient in 2016 harboring a germline‐activating mutation (R461C)." (PMID 34729943, 2021). "The first report of a CSF2RB‐activating “germline” mutation in leukemia patient confirmed the oncogenic potential of CSF2RB mutations in clinical samples." (PMID 34729943, 2021). "The first ever CSF2RB‐activating and tumorigenic mutation (but germline) in any clinical sample were reported in 2016 in leukemia." (PMID 34729943, 2021). "Though R461C CSF2RB was listed in the 1000 genomes database as an SNP (rs371045078) with low allele frequency, it has never been reported in cancer specimens until its first report in leukemia patient." (PMID 34729943, 2021). "Csf2rb encodes a common beta chain of the receptors of interleukin 3, interleukin 5, and granulocyte-macrophage colony-stimulating factor, and its partners’ expression has been described in specifically marking leukemia stem cells." (PMID 34638998, 2021). "It is becoming more widely acknowledged that the common beta chain CSF2RB cytokines are involved in the pathogenesis of various types of leukemia." (PMID 40837403, 2025). "They demonstrated that a targetable CSF2RB variation present in human leukemia promotes factor-independent growth, receptor phosphorylation and accumulation, and JAK/STAT pathway activation." (PMID 35574409, 2022). "In fact, we found that CSF2RB− IL1RL1+ cells showed significantly impaired colony-forming ability when grown in vitro, despite their robust ability to cause leukemia when transplanted into recipient mice." (PMID 30742053, 2019). "With the exception of CSF2RB− IL1RL1− KIT− cells, we found that each sub-population caused leukemia at both the 1,000 and 10,000 cell doses, indicating that each of these sub-populations contains LSCs." (PMID 30742053, 2019). "Mice transplanted with CSF2RB− IL1RL1− KIT− cells had the longest time to leukemia development and the lowest penetrance with statistically significant differences in survival as compared to mice transplanted with CSF2RB−, IL1RL1−, KIT+/− cells at the 10,000 cell dose." (PMID 30742053, 2019). "Moreover, CSF2RB is abnormally expressed in a variety of tumors, especially in leukemia." (PMID 40837403, 2025). "We sorted CM+, GFP+ leukemia cells for KIT and CSF2RB, markers we previously showed distinguish between these two populations in this mouse model, and performed PLA for RUNX1 and PTPB1." (PMID 41214140, 2026). "We found that the CSF2RB− IL1RL1+ KIT+ population had the highest BrdU incorporation rate, which correlated with the fastest leukemia development after transplantation." (PMID 30742053, 2019). "In the present study, we show that expression of the leukemogenic fusion gene Cbfb-MYH11 induces expression of IL1RL1 prior to CSF2RB, implying that IL1RL1 marks an earlier stage of leukemia development." (PMID 30742053, 2019). "Our finding that all LSC sub-populations recapitulate the heterogeneity of the original leukemia sample implies that the sub-populations defined by CSF2RB, IL1RL1, and KIT are likely not to be organized in a strict hierarchical differentiation scheme." (PMID 30742053, 2019). "Mice transplanted with the CSF2RB− IL1RL1+ KIT+ cells showed the shortest average life span and highest penetrance of leukemia development with statistically significant differences in survival as compared to mice transplanted with CSF2RB−, IL1RL1−, KIT+/−, or CSF2RB+ cells at the 10,000 cell dose." (PMID 30742053, 2019).
leukemia (continued). "We observed that the expression of CSF2RB, IL1RL1, and KIT in recipient leukemia samples was similar to that of the original, donor leukemia samples, regardless of the sub-population transplanted." (PMID 30742053, 2019).
asthma (5 papers, 2021 to 2024). "The CSF2RB locus was associated with asthma in a previous GWAS60." (PMID 34785669, 2021). "Among our genes that were driven by rare variants, i.e., ALOX15, CSF2RB, IL17RA, IL33, JAK2, S1PR4, and SH2B3, previous studies supported a rare variant association between IL33, which is a known asthma locus, and eosinophil count." (PMID 35935937, 2022).
schizophrenia (5 papers, 2012 to 2023). A major psychotic disorder characterized by abnormalities in the perception or expression of reality. "Among these putative ETV1 targets are CSF2RB, which has been associated with major depression and schizophrenia, and MIS18BP1, a gene implicated in the autism spectrum." (PMID 36449109, 2023). "Interestingly, associations between CSF2RB and schizophrenia and bipolar disorder have been recently found." (PMID 23094030, 2012). "IL3 receptors, including IL3RA and CSF2RB (or IL3RB), were also found significantly associated with schizophrenia in three different populations." (PMID 23226269, 2012).
breast carcinoma (4 papers, 2020 to 2025). "CSF2RB has a low somatic mutation rate in breast cancer samples/patients, with a frequency of approximately 0.4%." (PMID 40837403, 2025). "Across different cancer types, the mutation frequency of the CSF2RB gene is the highest in skin cutaneous melanoma (11.5%) and ranges from 0.38% to 1.26% in breast cancer subtypes." (PMID 40837403, 2025). "We have reported the novel somatic mutation CSF2RB S230I in one breast cancer cell line named KAIMRC1 and its source tumor tissue." (PMID 34729943, 2021). "This manuscript adopted an integrated strategy, including paired‐exome sequencing, pathway enrichment, and functional studies to discover novel somatic mutation CSF2RB S230I in a breast cancer cell line KAIMRC1 and related breast tumor." (PMID 34729943, 2021). "Other studies have shown that high CSF2RB expression is associated with an unfavorable prognosis in bladder and esophageal cancers, whereas it is related to a favorable prognosis in breast cancer, cervical squamous cell carcinoma and endo-cervical adenocarcinoma (CESC), and colon adenocarcinoma." (PMID 40837403, 2025). "However, functional studies are required to claim CSF2RB as a breast cancer hallmark gene or a potential therapeutic and prognostic candidate for breast cancer treatment." (PMID 40837403, 2025). "Wild-type CSF2RB shows higher expression than the mutated CSF2RB in breast cancer." (PMID 40837403, 2025). "Here, we report for the first time CSF2RB‐activating novel somatic mutation in breast cancer." (PMID 34729943, 2021). "Here, we report a similar but completely unknown somatic, potentially transforming, and oncogenic CSF2RB S230I mutation in breast cancer tissue and the established cell line KAIMRC1." (PMID 34729943, 2021). "Together, these findings conclude that CSF2RB S230I mutation could be actionable and might help in developing novel therapeutics for breast cancer patients." (PMID 34729943, 2021). "The present study is an attempt to understand the role of CSF2RB in breast cancer by collecting omics data from cancer genomic databases such as The Cancer Genome Atlas (TCGA), cBioPortal, TIMER2.0, GEPIA, and UALCAN." (PMID 40837403, 2025). "The CSF2RB promoter methylation level in tumor samples of breast carcinoma and its subtypes and normal samples revealed that tumor samples are hypermethylated, which can explain the low expression of CSF2RB in tumor samples." (PMID 40837403, 2025). "This manuscript seems to be a foundation stone for exploring CSF2RB as a druggable target in the context of breast cancer." (PMID 34729943, 2021). "The breast cancer cell line KAIMRC119 established from the patient’s breast tumor (harboring CSF2RB S230I) was able to survive and proliferate." (PMID 34729943, 2021). "The results suggest a diverse role for the CSF2RB gene across different subtypes of breast cancer." (PMID 40837403, 2025). "The data include gene expression profiles, mutations, methylation patterns, survival outcomes, and immune infiltration related to CSF2RB, specifically in breast cancer, and are compared to acute myeloid leukemia as a control since the role of CSF2RB in AML is well-established." (PMID 40837403, 2025). "In summary, somatic mutations in CSF2RB are not abundant in BRCA, suggesting a limited or inconsistent role as a driver in the tumor progression of breast carcinoma." (PMID 40837403, 2025). "It means that CSF2RB does not have a significant impact on the pathobiology of breast carcinoma." (PMID 40837403, 2025). "CSF2RB and seven other immune-related hub genes were identified to be molecular signatures in the subtype of triple-negative breast cancer (TNBC), which may be used as therapeutic targets to treat breast cancer." (PMID 40837403, 2025).
breast carcinoma (continued). "Here, we report the discovery of a novel somatic S230I CSF2RB mutation (i.e., neither present in 1000 genomes database, Exome Aggregation Consortium nor in the COSMIC database) in a breast cancer patient that tends to be potentially transforming and oncogenic mutation." (PMID 34729943, 2021). "The implications of CSF2RB in breast cancer remain unclear and have not been widely studied." (PMID 40837403, 2025).
inflammatory bowel disease (4 papers, 2022 to 2025). A spectrum of small and large bowel inflammatory diseases of unknown etiology. "Overexpression of CSF2RB in inflammatory bowel disease may exacerbate immune homeostasis imbalance by altering gut microbiota balance." (PMID 40777016, 2025).
lung carcinoma (4 papers, 2022 to 2023). "In the present study, the down-regulated gene CSF2RB was found associated with female LCNS compared to female lung cancer in smokers and its low expression in tumor tissues might be implicated in poor clinical outcome by a bioinformatics analysis." (PMID 37335631, 2023). "Overall, female lung cancer patients with low expression of CSF2RB were significantly correlated with a poor prognosis." (PMID 37335631, 2023). "Although recent bioinformatics studies have aimed to investigate hub genes for lung cancer and have reported that CSF2RB might be a survival-related gene of LUAD, limited research has been focused on “female” nonsmokers with lung cancer cohorts." (PMID 37335631, 2023). "Taken together, we could demonstrate that CSF2RB would be used as an important negative regulator of lung cancer progression." (PMID 35574409, 2022). "Finally, colony stimulating factor 2 receptor subunit beta (CSF2RB) has been shown to regulate epithelial-mesenchymal transition (EMT) in human lung cancer cells." (PMID 34870316, 2022). "The expressions of EMR3, NCF1, CSF2RB, DYSF, TLR8, and HCK in the lung cancer group were significantly different from those of the control group." (PMID 35923697, 2022).
pulmonary disease (4 papers, 2017 to 2021). "Similarly, a 3 kb insertion (20290_HX1_ins) is among two variants in a credible causal set for expression effects on CSF2RB, the dysfunction of which has been associated with pulmonary disease." (PMID 34528508, 2021). "The defects in CSF2RB are well related to a rare lung disorder called pulmonary surfactant metabolism dysfunction 5 (SMDP5, OMIM: 614370, aka pulmonary alveolar proteinosis 5, PAP5)." (PMID 34729943, 2021). "Statin therapy was associated with improvement in lung disease in autoimmune PAP patients, reduced cholesterol levels in alveolar macrophages from autoimmune PAP patients ex vivo, increased cholesterol efflux from Csf2rb−/− macrophages ex vivo, and ameliorated lung disease in Csf2rb−/− mice in vivo." (PMID 30087322, 2018).
acute myeloid leukemia (3 papers, 2022 to 2025). Acute myeloid leukemia (AML) is a group of neoplasms arising from precursor cells committed to the myeloid cell-line differentiation. "We used GEPIA to compare the CSF2RB gene expression between breast invasive carcinoma and acute myeloid leukemia and analyze the correlation between the pathological stage of breast invasive cancer and the expression of the CSF2RB gene." (PMID 40837403, 2025). "We carried out a heatmap of the overall survival of the CSF2RB gene in breast invasive carcinoma and acute myeloid leukemia." (PMID 40837403, 2025). "Our in silico analyses showed overexpression of CSF2RB in acute myeloid leukemia (AML) and decreased expression in breast invasive carcinoma (BRCA) compared to matched normal samples." (PMID 40837403, 2025). "GM-CSF receptors are expressed on 80% to 90% of acute myeloid leukemia (AML) patient samples, and there is evidence that CSF2RB is constitutively phosphorylated at S585 in AML." (PMID 36108743, 2022).
breast tumors (3 papers, 2021 to 2025). "CSF2RB S230I mutation in breast tumor seems to confer ligand‐independence to breast tumor cells and the KAIMRC1 cell line established from this breast tumor." (PMID 34729943, 2021). "Nevertheless, few other CSF2RB mutations are reported in breast tumors in the TCGA dataset hosted at the COSMIC database." (PMID 34729943, 2021). "In conclusion, CSF2RB S230I maybe a transforming and potentially oncogenic mutation in breast tumor." (PMID 34729943, 2021). "Promoter methylation across different ethnic populations shows that the CSF2RB promoter is hypermethylated in breast tumors of Caucasian, African-American, and Asian populations." (PMID 40837403, 2025). "In conclusion, CSF2RB is generally downregulated in breast tumor tissues, but its expression varies across different subtypes." (PMID 40837403, 2025). "IL-3 and GM-CSF receptor genes (IL3RA, CSF2RA, and CSF2RB) were expressed in human normal mammary epithelial and breast tumor cells at markedly higher levels compared with TSLP receptor (CRLF2)." (PMID 35657353, 2022). "While examining other breast tumors using Sanger sequencing (data not shown), we found 2 (tumors from unrelated individuals) out of 12 tumors (~16%) containing CSF2RB S230I mutation." (PMID 34729943, 2021). "S230I CSF2RB mutation is not frequent in the breast tumor specimen." (PMID 34729943, 2021).